NAMPT (nicotinamide phosphoribosyltransferase)
Diseases named in the same sentence as NAMPT in open-access papers (continued):
Sharing a sentence is not in itself a finding about the gene and the disease.
glioblastoma (continued). "We ectopically expressed NAMPT cDNA (Isoform A) in the human glioblastoma cell lines SF268 and U251MG, then selected transfectants to create a stable transfection pool (NAMPT)." (PMID 29245920, 2017). "We also found that glioblastoma grade IV tumors expressing high levels of NAMPT had a worse prognosis, which was confirmed in other datasets." (PMID 29245920, 2017). "Taken together, these results demonstrate that inhibition of NAMPT sensitizes glioblastoma cells to TMZ via activating ROS/JNK signaling pathway." (PMID 28097126, 2016). "As NAMPT overexpression has been reported in various tumor types, such as colorectal, ovarian, gastric, prostate, lung and glioblastoma, NAMPT inhibitors have been developed as potential anticancer agents." (PMID 26675378, 2016). "NAMPT inhibitor FK866 induced C6 glioblastoma cell death via inducing autophagic vacuoles, as well as induced nuclei malformation and mitochondria swelling." (PMID 28097126, 2016). "Interestingly, knockdown of NAMPT expression in the same glioblastoma cells (U87) as used in our study led to decreased cell proliferation, migration, and invasion and reduced tumor growth in-vivo." (PMID 37689115, 2023). "However, we note that this finding was based on NAMPT inhibitor treatment of different clones of one patient-derived glioblastoma cell line." (PMID 35628596, 2022). "Knockdown of NAMPT resulted in significantly reduced viability in IDH1R132H glioblastoma cells." (PMID 35628596, 2022). "Primary glioblastoma cell lines MGG119, MGG152,BT142, chondrosarcoma cell lines 30T, HT1080, SW1353, and gastric cancer cell lines MKN1, SNU668, Hs746T, SNU484, and SNU1750 with mutations have all been shown to be sensitive to NAMPT inhibition." (PMID 36160449, 2022). "We previously found that NAD+ restoration in glioblastoma cells utilizes the salvage pathways via NAMPT and NMRK1, while nicotinic acid phosphoribosyltransferase (NAPRT) and de novo synthesis from tryptophan via quinolinic acid phosphoribosyltransferase (QPRT) are not involved." (PMID 35628596, 2022). "Moreover, the IDH1-mutant cells had overall lower protein levels of NAMPT compared to IDH1-wildtype glioblastoma cells." (PMID 31888244, 2019). "NAMPT overexpression in experimental models of glioblastoma resulted in a cellular phenotype consistent with that of a cancer stem-like cell, while pharmacological and genetic inhibition of NAMPT decreased the ability of glioblastoma stem cells to self-renew and form in vivo tumors." (PMID 32010616, 2019). "However, the NAMPT protein and mRNA levels were higher in the glioblastoma cell lines than in the astrocytes." (PMID 31888244, 2019). "Therefore, we confirmed that NAMPT is a potent oncogene that confers CIC-like properties, which are responsible for the poorer responses and patient prognoses associated with glioblastoma." (PMID 29245920, 2017). "Altogether, our data suggest that NAMPT may be a suitable therapeutic target for glioblastoma, especially in patients with poor prognosis." (PMID 29245920, 2017). "Thus, we assessed the effect of NAMPT inhibitor on the TMZ-induced oxidative stress in glioblastoma cells." (PMID 28097126, 2016). "In the present study, we hypothesized that NAMPT inhibitor may sensitize glioblastoma cells to TMZ-induced cytotoxic effects." (PMID 28097126, 2016). "All these results indicate that NAMPT inhibitor sensitizes glioblastoma cells to TMZ." (PMID 28097126, 2016). "To validate this clinical observation in vitro, we measured NAMPT protein levels by Western blottingin a selection of 5 cell lines representative of different cancersincluding nonmelanoma skin (A431), liver (HepG2), lung (A549), skinmelanoma (A375), and glioblastoma (U87MG)." (PMID 38924492, 2024). "In tumors of patients with glioblastoma, NNMT outcompetes NAMPT, the enzyme responsible for NAD+ production, for nicotinamide." (PMID 41576167, 2026).
glioblastoma (continued). "Our study builds upon the growing body of evidence supporting the application of NAMPT inhibitors, particularly FK866, in targeting glioblastoma." (PMID 39336077, 2024). "This approach aims to enhance the efficacy of NAMPT’s inhibitor, FK866, in depleting NAD levels, inducing ATP depletion, and ultimately promoting glioblastoma cell death." (PMID 39336077, 2024). "NAMPT is the rate-limiting enzyme in the NAD salvage pathway, and E2F2 acts downstream of NAMPT and controls ID1 gene transcription to drive glioblastoma CSC self-renewal." (PMID 34476219, 2021). "Mesenchymal glioblastoma stem cells were found to preferentially upregulate NAMPT and NMMT expression through the transcription factor C/EBPβ, which interacts with NAMPT and NNMT gene regulatory regions." (PMID 34068917, 2021). "Lack of NAPRT expression in some tumors, such as neuroblastoma or glioblastoma, and lymphomas, places NAPRT as a biomarker for the use of NA as a chemoprotectant agent in the treatment with NAMPT inhibitors." (PMID 26675378, 2016). "This idea is supported by evidence from MYC-driven models where inhibition of glycolysis with LDHA inhibitors or inhibitors of the NAD+ salvage enzyme nicotinamide phosphoribosyl-transferase (NAMPT) led to selective toxicity in MYC-overexpressing pancreatic cancer and glioblastoma cells." (PMID 40126351, 2025). "NAMPT small-molecule inhibitors were shown to induce cytotoxicity through NAD+ depletion in a wide range of tumor models in vitro and in vivo (e.g., colorectal carcinoma, acute myeloid leukemia and glioblastoma)." (PMID 35628596, 2022). "Last but not least, NAMPT inhibitors augmented oxidative stress induced by temozolomide (TMZ) in glioblastoma cells, and this sensitization effect was reversed by the ROS scavenger tocopherol." (PMID 34068917, 2021). "Although the functional and prognostic role of NAMPT has not been well studied in cervical cancer, it is reported to predict prognosis in breast invasive ductal carcinoma, glioblastoma and colorectal cancer." (PMID 33160404, 2020). "Furthermore, NAMPT expression correlated with high levels of Nanog, CD133 and CIC-like cells in glioblastoma directly extracted from patients." (PMID 29245920, 2017). "We found that FK866 and CHS828, two distinct NAMPT inhibitors, increased the TMZ-induced apoptosis and necrosis, enhanced the TMZ-induced caspase-1, caspase-3, and caspase-9 activities, and augmented the TMZ-induced oxidative stress in glioblastoma cells." (PMID 28097126, 2016). "Therefore, NAMPT could also be an indicator of poor prognosis in HNSCC, as occurs in stomach cancer, colon cancer and glioblastoma." (PMID 36078035, 2022). "Increased expression of NAMPT and NNMT would allow glioblastoma cells to rapidly respond to sirtuin signaling and DNA damage and may in part explain chemotherapy and radiation resistance in glioblastoma stem-like cells." (PMID 35806160, 2022). "Interestingly, transduction with IDH1R132H led to an increased NAMPT expression in non-neoplastic astrocytes, which had overall low NAMPT levels compared to glioblastoma cells." (PMID 31888244, 2019).
melanoma (36 papers, 2011 to 2026). A malignant, usually aggressive tumor composed of atypical, neoplastic melanocytes. "Together, these data suggest that NAMPT over-expression positively influences the capacity of melanoma cells to grow even independently from the mutations on the key oncogene BRAF." (PMID 35272691, 2022). "NAMPT expression was reported to be associated with unfavorable overall survival in melanoma patients." (PMID 35565188, 2022). "Using the coefficients obtained by multivariate Cox analysis, the risk score of melanoma patients was calculated according to the following formula: risk score = (−0.097) × A2M + (−0.185) × NAMPT + (−0.123) × LIF + (−0.247) × EBI3 + (−0.170) × ERAP1." (PMID 35326741, 2022). "In BRAF-mutated melanoma cells, the inhibition of NAMPT, using FK866 and GMX1778, or its genetic knock-down, reduced cancer cell proliferation, both in vitro and in vivo, highlighting NAMPT as an actionable target for melanoma patients with BRAF mutations." (PMID 36077374, 2022). "A recent paper highlights NAMPT as a critical molecule in priming pro-tumor functions of tumor-associated neutrophils (TANs) in melanoma, including tumorigenic conversion of TANs and their pro-angiogenic switch." (PMID 34073463, 2021). "Based on our previous data, which indicated that BRAFi-resistant cells over-express NAMPT, we wondered what the effects were of NAMPT over-expression in BRAF V600E mutated melanoma cells." (PMID 33419372, 2020). "In BRAF-mutated melanoma, the high expression of NAMPT is associated with targeted therapy resistance, and NAMPT is a therapeutic target for this subset of patients." (PMID 32005247, 2020). "Clinically, higher NAMPT expression is associated with worse prognosis correlating with tumor growth, metastases and cellular dedifferentiation in melanoma." (PMID 31119097, 2019). "NAMPT has also been shown to be upregulated in tumor associated neutrophils (TANs) in patients with melanoma and head and neck cancer, and in murine cancer models." (PMID 32010616, 2019). "The choice of melanoma derives from our recent study, which indicates that NAMPT becomes the dominant NAD-biosynthetic enzyme in BRAF-resistant melanoma cell lines and patients BRAF-mutated." (PMID 29721178, 2018). "Our recent data indicate that NAMPT becomes the master regulator of NAD synthesis in BRAF-mutated melanoma cells that acquire resistance to BRAF inhibitors (BRAFi)." (PMID 29721178, 2018). "Our recent data indicate that the acquisition of BRAF resistance in BRAF-mutated metastatic melanoma cells is accompanied by a significant increase of intracellular NAMPT (iNAMPT), which becomes the master regulator of NAD biosynthesis." (PMID 29721178, 2018). "NAMPT was found to be upregulated in tumor-associated neutrophils from melanoma patients." (PMID 35565188, 2022). "Furthermore, inhibition of BRAF in susceptible cells results in downregulation of NAMPT transcription, whereas increase of NAMPT expression makes melanoma cells resistant to BRAF inhibitors." (PMID 36160449, 2022). "Moreover, melanoma cells resistant to BRAF inhibitors (BRAFi) were unusually sensitive to inhibitors targeting NAMPT, which caused decreased cellular NAD levels." (PMID 34068679, 2021). "IFN-γ increases the expression of nicotinamide phosphoribosyltransferase (NAMPT), an enzyme involved in NAD+ biogenesis, which is associated with the metabolic reprogramming of melanoma cells and increased melanoma growth in vivo." (PMID 40108693, 2025). "The involvement of NF‐kB pathways through NAMPT genes is also highlighted within the context of melanoma pathophysiology." (PMID 39823244, 2025). "Our work unveils an unforeseen tumor-suppressing role for mTORC2 in the early adaptation phase of BRAFV600E melanoma cells to targeted therapy and identifies the NAMPT-ETC axis as a potential therapeutic vulnerability of low RICTOR tumors." (PMID 38755661, 2024).
melanoma (continued). "RICTOR deficiency alters post-translational modifications in NAMPT likely affecting its activation and/or stability, which is suggestive of a complex interplay between mTORC2 signaling and NAD+ biosynthesis in melanoma." (PMID 38755661, 2024). "We also demonstrated that IFNγ-inducible NAMPT in melanoma cells counteracts the growth-suppressive effects of IFNγ." (PMID 36900204, 2023). "We show that IFNγ signaling upregulates NAMPT in melanoma cells, increasing cell proliferation and survival." (PMID 36900204, 2023). "High levels of both iNAMPT and visfatin/eNAMPT were expressed in BRAFi-resistant melanoma cells, while transcriptional downregulation of NAMPT was reported in BRAFi-sensitive cells." (PMID 38116009, 2023). "Melanoma cells have increased NAMPT expression, and NAMPT inhibition significantly reduces melanoma cell proliferation." (PMID 36900204, 2023). "Altogether, these data indicate that the inhibition of IFNγ-induced NAMPT leads to cell death in melanoma." (PMID 36900204, 2023). "Further, NAMPT is also known to be secreted from cells and is referred to as extracellular NAMPT (eNAMPT), and the mechanism by which IFNγ alters eNAMPT in melanoma will also be of interest for future studies." (PMID 36900204, 2023). "We treated B16-F10 mouse melanoma cells with IFNγ for 6 or 24 h, which significantly increased NAMPT mRNA expression." (PMID 36900204, 2023). "Altogether, we showed strong evidence that IFNs induce NAMPT in mouse and human melanoma cells, suggesting that the IFN-mediated metabolic changes are, in part, mediated by differentially regulated NAMPT." (PMID 36900204, 2023). "We demonstrate that interferon gamma (IFNγ) mediates the metabolic reprogramming of melanoma cells by inducing the essential NAD+ salvage pathway enzyme nicotinamide phosphoribosyltransferase (NAMPT) gene through STAT1 binding to the NAMPT locus." (PMID 36900204, 2023). "IFNγ and FK866 combination treatment significantly decreased melanoma growth, but we wanted to assess the contribution of IFNγ-inducible NAMPT in melanoma growth, specifically." (PMID 36900204, 2023). "Analyzing only NAMPT gene, it is evident that it is more frequently subjected to gain/amplification in melanoma compared to control-matched samples." (PMID 35272691, 2022). "Recently, we and others demonstrated that NAMPT is one of the main players in driving BRAFi resistance and melanoma plasticity, mediating metabolic adaptation, reshuffling of the epigenetic landscape and forcing an invasive/mesenchymal/stemness phenotype." (PMID 35272691, 2022). "NAMPT over-expression as intracellular enzyme in melanoma compared to melanocytes has been demonstrated by several studies." (PMID 36077374, 2022). "NAMPT over-expression induces also metabolic rewiring financing increased NAD levels, transcriptomic, and epigenetic reshuffling that steer melanoma cells toward an invasive phenotype associated with the onset of resistance to targeted therapies." (PMID 36077374, 2022). "Although experimental data in melanoma to our knowledge are currently missing, in hepatocarcinoma, pancreatic cancer, and multiple myeloma models pharmacological inhibition of NAMPT results in an inhibition of mTORC1 activity." (PMID 36077374, 2022). "To directly determine the pro-tumorigenic effect of NAMPT we over-expressed the enzyme in the melanoma Mewo cell line (BRAF-WT) and in NIH-3T3 (murine immortalized fibroblasts), very commonly exploited in this kind of experiments." (PMID 35272691, 2022). "Overall, these data confirm that NAMPT plays a central role in phenotypic plasticity of melanoma and during the onset of resistance, suggesting a rational to target this enzyme in melanoma patients in combination with targeted- and immuno-therapy." (PMID 36077374, 2022).
melanoma (continued). "In BRAFV600E melanoma cells, the inhibition of NAMPT reduced cancer cell proliferation both in vitro and in vivo, whereas forced NAMPT expression resulted in drug resistance to PLX4032, a potent inhibitor of the BRAFV600E oncogene." (PMID 35565188, 2022). "In the last 10 years, increasing evidence has supported a driving role of NAMPT in melanoma progression and drug resistance." (PMID 34073463, 2021). "In melanoma, NAMPT is secreted by the cancer cells and NAMPT silencing was shown to reduce tumor progression and was accompanied by lower levels of circulating eNAMPT." (PMID 34068917, 2021). "Overall, these data confirm that NAMPT plays a central role in the phenotypic plasticity of melanoma, becoming a novel therapeutic target in the clinical setting." (PMID 34073463, 2021). "The overexpression of NAMPT was observed in the vertical growth phase and in melanoma metastases when compared to melanocytes." (PMID 34068679, 2021). "NAMPT was first identified as over-expressed in melanoma lesions compared to benign lesions at the transcriptional and protein levels." (PMID 34073463, 2021). "Other research confirmed a higher expression of NAMPT in melanoma in comparison to melanocytes, as well as in biopsies from patients with BRAFi as compared to before the acquisition of resistance." (PMID 34068679, 2021). "To answer this question, we used BRAF V600E melanoma cell lines (A375 and M14) modified to stably over-express NAMPT (NAMPT/GFP) and functionally studied their behavior by comparing them to control GFP and BRAFi-resistant (/BiR) cells." (PMID 33419372, 2020). "The direct correlation between NAMPT expression and gene set enrichments involving metastasis, invasiveness and mesenchymal/stemness properties were verified also in melanoma patients by analyzing The Cancer Genome Atlas (TCGA) datasets." (PMID 33419372, 2020). "To understand the functional role of NAMPT in the BRAFi resistance program and melanoma aggressiveness, we generated MM cell lines that over-expressed NAMPT in a stable or inducible way." (PMID 33419372, 2020). "Our previous data showed that treatment of melanomas with NAMPT inhibitors (NAMPTi) led to a metabolic crash decreasing NAD and ATP levels and ultimately inducing apoptosis in vitro and tumor regression in a xenograft model." (PMID 33419372, 2020). "NAMPT was reported to be upregulated in several malignant cancers, including prostate, breast, melanoma, colon, and hematologic malignancies." (PMID 32005247, 2020). "Decrease in NAMPT enzyme directly leads to blockage of the energy pathways in G-361 cells and indicates melanoma reduction." (PMID 31126298, 2019). "The CAP alone and the co-treatment group showed a reduced level of NAMPT significantly upto 50% as as compared to the control group attributable to the reduction in melanoma." (PMID 31126298, 2019). "We placed particular emphasis on Daporinad, a NAMPT inhibitor with previously reported antitumor activity and favorable safety profiles in early-phase clinical trials for refractory B-cell chronic lymphocytic leukemia and advanced melanoma." (PMID 40563807, 2025). "Overall, our analysis revealed that RICTOR deficiency is coupled to an increased NAMPT protein expression and/or activity in BRAFV600E melanoma cells, and that both transcriptional and post-transcriptional mechanisms can account for this effect in a cell lineage-specific manner." (PMID 38755661, 2024).